LINC01087 (long independently transcribed non-coding RNA 1087)
Synonyms: ERLC1
Gene: Long non-coding RNA gene on chromosome 2 (131,637,025 to 131,649,615, forward strand). Ensembl gene ENSG00000224559.
Diseases named in the same sentence as LINC01087 in open-access papers:
LINC01087 is named in the same sentence as 18 diseases in open-access papers, as found by Europe PMC text mining. Sharing a sentence is not in itself a finding about the gene and the disease. The quoted sentences say what the papers report.
breast carcinoma (10 papers, 2020 to 2025). "LINC01087 has been reported to be highly expressed in breast cancer tissues compared to tumor-adjacent tissues, and survival analysis has shown that high expression of LINC01087 is associated with poor prognosis." (PMID 41163216, 2025). "A series of in-depth in silico analyses revealed LINC01087 as a potential diagnostic indicator of some hormone-related tumors, including breast cancer (BC), ovarian carcinoma, and testicular germ cell tumors, as well as other cancer histotypes, such as esophageal and stomach cancers." (PMID 36497462, 2022). "In another study, LINC01087 was significantly increased in breast cancer and its downregulation inhibited the malignant tendency of breast cancer." (PMID 39023191, 2024). "LINC01087 is enhanced in breast cancer, and LINC01087 affects ROCK1 expression by sponging miR-335-5p, thereby affecting migration and invasion of breast cells." (PMID 35646642, 2022). "LINC01087 is enhanced in breast cancer, and LINC01087 affects the expression of ROCK1 by sponging miR-335-5p, thus affecting the migration and invasion of breast cells." (PMID 33968763, 2021). "LINC01087 is highly expressed in breast cancer, indicating a poorer survival time of patients." (PMID 34817752, 2022). "In addition, Kaplan–Meier plotter analysis showed that TNBC patients with low Linc011087 levels displayed positive lymph node status but patients with luminal breast cancer and high Linc01087 expression had extended relapse free survival (RFS)." (PMID 36139687, 2022). "LINC01087 imposes the carcinogenic effect on breast cancer, which is negatively related to the patient’s prognosis, and could modify the biological functions of cells." (PMID 34817752, 2022). "Accordingly, LINC01087 expression has been identified to upregulate in luminal breast cancer." (PMID 34817752, 2022).
glioma (3 papers, 2021 to 2022). A benign or malignant brain and spinal cord tumor that arises from glial cells (astrocytes, oligodendrocytes, ependymal cells). "High expression of LINC01087 was associated with poor prognosis of glioma patients with preoperative MRI." (PMID 34817752, 2022). "Mechanistically, it has been demonstrated that LINC01087 participates in the development of glioma by targeting some microRNAs (miRNAs) (i.e., miR-384 and miR-1277-5p) and, therefore, altering the related signaling pathways." (PMID 36497462, 2022). "LINC01087 has prognostic significance in glioma and silencing LINC01087 deters glioma development through elevating miR-1277-5p to reduce ACER3 expression." (PMID 34817752, 2022). "Afterwards, we designed LINC01087 silencing in vitro experiments and found that decreasing LINC01087 impaired proliferation, invasion, and migration but augmented apoptosis of glioma cells." (PMID 34817752, 2022). "For instance, it has been demonstrated in vitro that a high expression of LINC01087 reduces the level of Bcl2 by acting as a miR-384 sponge, thus promoting apoptosis in glioma cells." (PMID 36497462, 2022). "The contribution of LINC01087 to the pathogenesis of cancer, as well as its pivotal role as a biomarker, has been described only in a few oncological indications (i.e., BC, glioma, esophageal squamous cell carcinoma, and thyroid cancer)." (PMID 36497462, 2022). "We measured LINC01087 expression in 80 patients with glioma and found that LINC01087 was upregulated in glioma tissues." (PMID 34817752, 2022). "Recent evidence reported LINC01087 to be overexpressed in glioma patients with respect to healthy subjects." (PMID 36497462, 2022). "This suggested that LINC01087 acted as miR-384 sponge, regulated Bcl-2 to inhibit the growth of glioma cells and induced apoptosis, which was a potential target of glioma." (PMID 34459789, 2021). "Meanwhile, the depletion of LINC01087 by sh-LINC01087#1 enhanced the relative caspase-3 activity in the glioma cells." (PMID 34459789, 2021). "To further understand the mechanism of LINC01087 in glioma, we established sh-LINC01087#1 plasmid to observe its effect on glioma cell growth." (PMID 34459789, 2021). "Flow cytometry and WB experiments confirmed that the apoptosis rate of glioma cells decreased and the expression of apoptosis-related proteins increased after knocking down LINC01087." (PMID 34459789, 2021). "To further understand the role of LINC01087 in glioma, we established sh-LINC01087 plasmid and transfected sh-LINC01087#1 into U87 and U251 cells." (PMID 34459789, 2021). "So, the goal of this research is to determine the role of LINC01087 in gliomas and to provide potential targets for clinical treatment." (PMID 34459789, 2021). "LINC01087 expression was found to upregulate in patients with glioma." (PMID 34817752, 2022). "For these reasons, we examined the prognostic value of LINC01087 in glioma and also explored whether LINC01087/miR-1277-5p/ACER3 axis could modulate the biological activities of glioma cells." (PMID 34817752, 2022). "Moreover, rescue assays reveal that miR-1277-5p overexpression (or ACER3 overexpression) reversed the effects of LINC01087 upregulation (or miR-1277-5p upregulation) on glioma cells." (PMID 34817752, 2022). "Shortly, reducing LINC01087 levels in glioma cells restrained tumor malignancy." (PMID 34817752, 2022). "In short, LINC01087-mediated pro-tumorigenesis in glioma could be reduced by overexpressing miR-1277-5p or suppressing ACER3." (PMID 34817752, 2022). "The present research also verified that LINC01087 could bind to miR-1277-5p to lower miR-1277-5p expression in glioma cells." (PMID 34817752, 2022). "However, much more efforts are still required to explore the downstream signaling pathways related to the progression of glioma mediated by the LINC01087/miR-1277-5p/ACER3 axis." (PMID 34817752, 2022). "After that, we found that LINC01087 was primarily situated in the cytoplasm of glioma cells." (PMID 34459789, 2021).
glioma (continued). "Therefore, this research aims to probe into LINC01087’s expression and potential mechanism in glioma and provide potential targets for clinical treatment." (PMID 34459789, 2021). "Furthermore, LINC01087 silencing can obviously suppress the proliferation of glioma cells and induce apoptosis." (PMID 34459789, 2021). "This suggested that LINC01087 could take part in glioma growth through miR-384/Bcl-2 axis (*P < 0.05)." (PMID 34459789, 2021). "To study whether LINC01087 could regulate miR, we first determined its localization in glioma cells by fluorescence in situ hybridization." (PMID 34459789, 2021). "Our study found that the LINC01087 expression in glioma increased obviously, which suggested that it might regulate the occurrence of glioma." (PMID 34459789, 2021). "In this experiment, we found that the LINC01087 expression in glioma tissues and cells increased obviously, and it could act as miR-384 sponge and participate in the development of glioma by regulating Bcl-2." (PMID 34459789, 2021). "We discovered that LINC01087 was also highly expressed in glioma through GEO (gene expression omnibus) chip analysis, and predicted that it might mediate miR-384/Bcl-2 axis to take part in the development of glioma." (PMID 34459789, 2021). "However, we found that the proliferation and cloning of glioma cells decreased after knocking down LINC01087." (PMID 34459789, 2021). "In addition, by detecting the expression in glioma cell lines, we also discovered that the LINC01087 relative level in U87, SHG-44, U251 and H4 cells increased markedly." (PMID 34459789, 2021). "The glioma patients were divided into high expression group (n = 36) and low expression group (n = 44) according to the average LINC01087 expression level, and the correlation between LINC01087 expression and clinical parameters of glioma patients was determined." (PMID 34817752, 2022). "Thus, we searched the prognostic value and functional action of LINC01087 in glioma." (PMID 34817752, 2022). "It's unclear whether LINC01087 has the same mechanism in glioma." (PMID 34459789, 2021). "Furthermore, in our correlation analysis, we found that miR-384 was negatively correlated with Bcl-2 and LINC01087, which suggested that LINC01087/miR-384/Bcl-2 axis might exist in glioma progression." (PMID 34459789, 2021). "It indicated that LINC01087 might be a potential therapeutic target for glioma." (PMID 34459789, 2021). "It suggested that LINC01087 could suppress the growth of glioma by regulating miR-384/Bcl-2 axis." (PMID 34459789, 2021). "Besides, we confirmed the mechanism of LINC01087 in glioma, but there are still some limitations." (PMID 34459789, 2021). "The LINC01087 and ACER3 expression was in up-regulation and the miR-1277-5p expression was in down-regulation in clinical glioma samples." (PMID 34817752, 2022). "By analyzing the LINC01087 expression in GSE103229 expression profiling, we found that the expression in glioma increased dramatically." (PMID 34459789, 2021). "In this research, we evaluated the fundamental effects of LINC01087/miR-1277-5p/ACER3 axis in glioma cell growth, and attained the main observation illustrating that LINC01087 facilitated the biological behaviors of glioma cells by binding to miR-1277-5p to silence ACER3." (PMID 34817752, 2022). "In this study, we found that LINC01087 could act as miR-384 sponge by dual-luciferase report and RIP experiment, and the miR-384 expression in glioma cells increased obviously after knocking down LINC01087." (PMID 34459789, 2021).
ovarian carcinoma (2 papers, 2022). A malignant neoplasm originating from the surface ovarian epithelium. "Notably, a high expression of LINC01087 exhibits a strong diagnostic value in breast, esophageal, stomach, and ovarian carcinomas." (PMID 36497462, 2022). "Our results revealed that LINC01087 is mainly upregulated in multiple cancers, particularly in BC, esophageal, stomach, and ovarian carcinomas, as well as in testicular germ cell tumors." (PMID 36497462, 2022).
thyroid cancer (2 papers, 2022 to 2024). "For example, one study reported increased LINC01087 expression in thyroid cancer and demonstrated that its silencing reduced the aggressiveness of cancer cells." (PMID 39023191, 2024). "The biological role and downstream regulatory mechanism of LINC01087 in thyroid cancer was further studied." (PMID 35368894, 2022). "LINC01087 was highly expressed in thyroid cancer tissues (5.077 ± 1.267) compared with adjacent control tissues (1.250 ± 0.379, n = 30, p < 0.01)." (PMID 35368894, 2022). "Results indicate that the high expression of LINC01087 can be used as a specific marker of thyroid cancer and has important value for the early diagnosis of thyroid cancer." (PMID 35368894, 2022). "The localization of LINC01087 in the cytoplasm of thyroid cancer cells was determined using the FISH method." (PMID 35368894, 2022). "LINC01087 was highly expressed in thyroid carcinoma tissues, and its expression was higher than that in paracarcinoma tissues." (PMID 35368894, 2022). "In addition, LINC01087 silencing suppressed thyroid cancer cell proliferation, invasion, and EMT via the miR‐135a‐5p/PPM1E axis." (PMID 39023191, 2024). "This study investigated the expression of LINC01087 in thyroid cancer." (PMID 35368894, 2022). "In conclusion, LINC01087 affects the development and progression of thyroid cancer." (PMID 35368894, 2022). "LINC01087 can promote the proliferation and apoptosis of thyroid cancer cells, and its mechanism may be related to the miR-135a-5p/PPM1E axis." (PMID 35368894, 2022). "However, this study may have some defects, and further studies should focus on the mechanism of LINC01087's involvement in the EMT of thyroid cancer." (PMID 35368894, 2022). "LINC01087 knockdown and the high expression of miR-143-3p inhibited the proliferation, invasion, and EMT processes of TPC-1 and K1 in thyroid cancer cells." (PMID 35368894, 2022). "In comparison with normal thyroid tissues and cells, the expression level of LINC01087 in thyroid cancer tissues and TPC-1 and K1 cells increased, and the expression level of miR-135a-5p in thyroid cancer tissues and TPC-1 and K1 cells decreased." (PMID 35368894, 2022). "The role of LINC01087 in thyroid cancer has not been reported." (PMID 35368894, 2022). "Therefore, LINC01087 may regulate the expression of PPM1E through miR-135a-5p, thereby affecting the proliferation and metastasis of thyroid cancer cells." (PMID 35368894, 2022).
renal papillary cell carcinoma (1 paper, 2022). "Moreover, LINC01087 appears as a prognostic indicator in BC and renal papillary cell carcinoma." (PMID 36497462, 2022). "Additionally, LINC01087 could serve as a prognostic indicator in BC and papillary renal cell carcinoma." (PMID 36497462, 2022).
testicular germ cell tumor (1 paper, 2022). A germ cell tumor arising from the testis. "By contrast, LINC01087 demonstrated a strong downregulation in testicular germ cell tumors (TGCT, log2FC = −6.1, p = 6.59e-73)." (PMID 36497462, 2022). "By contrast, LINC01087 displayed downregulation in testicular germ cell tumors (TGCT)." (PMID 36497462, 2022).
cancer (5 papers, 2020 to 2024). A tumor composed of atypical neoplastic, often pleomorphic cells that invade other tissues. "Out of the 7 cancers harboring an aberrant expression of LINC01087, a diagnostic test revealed promising performances in 5 of them (i.e., ROC curve AUC > 0.7)." (PMID 36497462, 2022). "In silico analyses indicated that deregulation of LINC01087 in cancer was associated with a modulation of genes related to ion channel, transporter, and peptide receptor activity." (PMID 36497462, 2022). "We identified 2 transcripts that were positively associated with LINC01087 expression in all 5 cancers: the pseudogene POTE ankyrin domain family member K (POTEKP) and the uncharacterized lncRNA AC093838.1." (PMID 36497462, 2022). "Multiple studies have demonstrated that LINC01087 promotes carcinogenesis by regulating various cellular processes in a range of human cancers." (PMID 39023191, 2024). "To capture significant insights into LINC01087 functions in cancers, we performed a correlation-based expression analysis extracting data from TCGA datasets." (PMID 36497462, 2022). "Here, we explored the clinical interest of LINC01087 in the diagnosis and prognostication of multiple cancer types." (PMID 36497462, 2022). "In the present report, bioinformatics analyses uncovered the role of LINC01087 in the diagnosis and prognostication of different human cancers." (PMID 36497462, 2022). "We proceeded by evaluating the potential functional significance of LINC01087 in the 5 cancer types in which it was most upregulated, namely, BC, ESCA, OV, STAD, and TGCT." (PMID 36497462, 2022). "These similarities support an intimate link between the solute carrier family and LINC01087 in cancer." (PMID 36497462, 2022). "Regarding the up-regulated lncRNAs, only a low number of them have been previously implicated in cancer, such as the up-regulated CASC15, LINC00662, LINC01272, LINC00857, LINC00092, LINC00673 and the down-regulated LINC00657, LINC01087 and LINC00993." (PMID 32753692, 2020). "As widely described, LINC01087 aids in the growth of several cancer types." (PMID 39023191, 2024). "In summary, this orthogonal investigation revealed that LINC01087 might impact cancer progression by modulating the ability of cells to interact with their environment." (PMID 36497462, 2022). "Moreover, our study revealed the potential of LINC01087 (and perhaps other lncRNAs) to regulate neuroactive molecules in cancer." (PMID 36497462, 2022). "It is reported that LINC01087 is highly expressed in cancer and participates in tumorigenesis." (PMID 34459789, 2021). "Furthermore, the involvement of LINC01087 in cancer development might be related to its direct and indirect (miRNA-mediated) role in modulating biochemical exchanges between the intracellular milieu and the surrounding microenvironment." (PMID 36497462, 2022). "LINC01087 was highly expressed in LUAD, and its downregulation restrained cancer cell proliferation, migration, invasion, and epithelial–mesenchymal transition in vitro as well as tumor growth in a xenograft tumor model." (PMID 39023191, 2024). "In addition, some non-coding RNAs, such as LINC01087 56, TUG1 27, NEAT1 57 and circ_0020123 58, were verified to target miR-384 in cancer progression." (PMID 39132166, 2024). "LINC01087 demonstrated significant upregulation (|log2 FC| ≥ 1.5, p ≤ 0.05) in 6 out of the 30 cancers as compared to their normal (i.e., non-tumor or healthy) tissue counterparts." (PMID 36497462, 2022).
tumor (5 papers, 2021 to 2025). "LINC01087 expression appeared to be significantly associated with the tumor status (p = 0.04) and tumor size (p = 0.01) in BC." (PMID 36497462, 2022). "In addition, the transcript of mediator complex subunit 15 pseudogene 4 (MED15P4) showed a strong association with LINC01087 in 3 out of the 5 tumor types (i.e., OV, STAD and TGCT), and a moderate correlation in ESCA." (PMID 36497462, 2022). "Finally, we investigated whether the deregulation of LINC01087 could be associated with clinicopathological features (i.e., age, gender, tumor stage, tumor size, tumor status, lymph node, and metastasis involvement)." (PMID 36497462, 2022). "Nude mice were injected with LUAD cells with stable LINC01087 knockdown to further examine the function of LINC01087 on LUAD tumor formation in vivo." (PMID 39023191, 2024). "In summary, the deregulation of LINC01087 plays a potential role in the diagnosis and prognosis of different tumor types." (PMID 36497462, 2022). "To this aim, we performed GO annotation and KEGG enrichment analyses on the set of genes correlated with LINC01087 expression in the 5 tumor types (n = 2458, |R| ≥ 0.1, p ≤ 0.05)." (PMID 36497462, 2022). "Additionally, the levels of the proliferation marker Ki67 and CEP55 in tumor tissues were markedly decreased by LINC01087 knockdown." (PMID 39023191, 2024). "Altogether, these results documented a constellation of both protein-coding and translation-interfering transcripts that are directly or indirectly regulated by LINC01087 and that might contribute to the initiation and progression of neoplasms." (PMID 36497462, 2022). "At first sight, we screened for genes correlated with LINC01087 expression in the 5 tumor types." (PMID 36497462, 2022). "LINC01087 knockdown reduced LINC01087 and CEP55 expressions and increased miR‐514a‐3p expression in tumor tissues." (PMID 39023191, 2024). "Herein, our analyses revealed that LINC01087 was significantly upregulated in LUAD tissues and cells and that LINC01087 knockdown restrained proliferation, migration, invasion, and EMT and enhanced apoptosis in LUAD cells and reduced tumor development in vivo." (PMID 39023191, 2024). "Tumor growth was slower in mice injected with LUAD cells with stable LINC01087 knockdown than in those injected with LUAD cells without stable LINC01087 knockdown." (PMID 39023191, 2024). "Furthermore, LINC01087 knockdown reduced GTP‐RhoA and ROCK1 levels in tumor tissues." (PMID 39023191, 2024).
LINC01087 also shares sentences with these, for which no sentence is quoted: lung adenocarcinoma (2 papers); esophageal carcinoma (1); hepatocellular carcinoma (1); lung squamous cell carcinoma (1); rectum adenocarcinoma (1); renal cell carcinoma (1); skin cutaneous melanoma (1); stomach adenocarcinoma (1); stomach cancers (1); uterine carcinosarcoma (1).